SOX2 (SRY-box transcription factor 2)
Diseases named in the same sentence as SOX2 in open-access papers (continued):
Sharing a sentence is not in itself a finding about the gene and the disease.
lung carcinoma (continued). "As expected, SOX2 signal was identified only in the tumor (CK-positive) compartment of lung carcinoma samples and showed a predominant nuclear staining pattern." (PMID 23620753, 2013). "SOX2 protein levels were measured in tissue microarrays (TMAs) containing FFPE samples from two independent lung cancer cohorts (n = 340 & 307) using automated quantitative immunofluorescence (QIF)." (PMID 23620753, 2013). "Taken together, these results validated the X-tile defined cutpoint for SOX2 score stratification in lung carcinoma samples." (PMID 23620753, 2013). "Aside from the Sox2, the expression of Sox4 was also elevated in several types of cancer, in which lung cancer had the greatest levels of Sox4 expression." (PMID 23443092, 2012). "Having identified the function of SOX2 in the tumorigenesis property of lung cancer cells and its target oncogenes, we then tested all the other targeted genes by RNA-Seq and found 246 cancer genes." (PMID 22615765, 2012). "Here we also present evidence indicating that SOX2 plays an important role in carcinogenesis of lung cancer." (PMID 22615765, 2012). "The current results demonstrate that Sox2 and Oct4 can be detected in human lung cancer by IHC, Western blot and RT-PCR." (PMID 22837720, 2012). "The first model was used in our study to observe SOX2’s function in the tumorigenesis of lung cancer in vivo, which reflected the whole process of homing and proliferation of tumor cells in lung." (PMID 22615765, 2012). "Among them, the role of Sox2 gene in lung cancer is the one best recognized, which is relevant to aggressive tumor behavior, poor outcome, and/or the increasing risk of recurrence." (PMID 23443092, 2012). "Our study supports the notion that silencing of the SOX2 gene is an effective strategy for human lung cancer therapy." (PMID 22615765, 2012). "Following the identification of SOX2’s function on tumorigenesis and its regulatory effect on expression of oncogenes in human lung cancer cells, we next explored its function in vivo." (PMID 22615765, 2012). "In their study, the upregulation of Sox2 and Oot4 in the side population (SP) cells of lung cancer led the cancer cells to shift to CSCs." (PMID 23443092, 2012). "Predominantly higher expression of SOX2 was found in both NSCLC and SCLC than in normal/paracarcinoma tissues (p<0.001), indicating the important role of SOX2 in the tumorigenesis of lung cancer." (PMID 22615765, 2012). "This study also supports the notions that targeting of SOX2 is an effective strategy for lung cancer therapy." (PMID 22615765, 2012). "The potential role of Sox2 gene in lung cancer was further supported by a recent finding of identification of Sox2 as a frequently amplified gene." (PMID 23443092, 2012). "Together, our findings suggest that the SOX2 signalling pathway in CSCs derived from D121 lung cancer cells is activated and has a key role in the development and maintenance of cancer stem cells." (PMID 21468047, 2011). "In fact, the key role played by transcription factor SOX2 in this regard was clearly indicated when D121 lung cancer cells, subjected to SOX2 knock down in vitro, were subsequently injected i.v. into syngenic C57BL/6 mice." (PMID 21468047, 2011). "In order to assess the transcriptional similarity of the alveolar carcinomas to human squamous cell lung cancer, we performed quantitative PCR for additional transcripts that cluster closely with Sox2 in the Duke lung cancer microarray dataset." (PMID 20548776, 2010). "Given the importance of Sox2 in the maintenance of stem cell phenotypes, its expression in lung epithelium, and its overexpression in a variety of tumors, we sought to define the potential role of Sox2 in mouse and human lung cancer." (PMID 20548776, 2010). "Additionally, the SOX2 transcription factor is involved in tumor development and the maintenance of pluripotency in human lung cancer." (PMID 40287470, 2025).
lung carcinoma (continued). "Furthermore, SLC7A11 expression is also directly stimulated by the stem cell transcription factor SOX2 in lung cancer stem-like cells (CSLCs)." (PMID 39875356, 2025). "Likewise, the mRNA results showed that SM-3 substantially reduced the levels of the transcription factors OCT4, NANOG, and SOX2 compared to Res-treated lung cancer cells, including H292 and H460 cells." (PMID 40287470, 2025). "SOX2 plays a critical role in the initiation and progression of lung cancer." (PMID 39976818, 2025). "Furthermore, SM-3 treatment led to a significant reduction in the levels of stem cell markers CD133 and CD44, as well as the stem cell transcription factors OCT4 and SOX2, compared to the spheroids treated with Res (50 μM) in lung cancer cells." (PMID 40287470, 2025). "Likewise, in lung cancer, SOX2 has a role in controlling cellular plasticity and the tumor cells’ capacity to adjust to changes in their surroundings, which helps them survive even under harsh circumstances." (PMID 41155227, 2025). "However, mutations within the SOX2 gene lead to a downregulation of SLC7A11 expression, hence increasing the vulnerability of lung cancer cells to ferroptosis." (PMID 39875356, 2025). "Additionally, SM-3 treatment resulted in decreased expression of stem cell markers (CD133, CD44, and ALDH1A1) and transcription factors (OCT4, NANOG, and SOX2) in spheroids and organoids from human lung cancer cells by inhibiting the mTOR/pAkt pathway." (PMID 40287470, 2025). "Furthermore, upregulation of Sox2 in a hypoxic environment can promote CD133 expression in lung cancer cells." (PMID 38672078, 2024). "Additionally, abnormal activation of the c-Met-SOX2 axis, mediated by sialylated IgG, enhances the stemness of lung cancer cells." (PMID 38632255, 2024). "Similarly, coculturing lung cancer cells with THP1-derived macrophages resulted in significant increases in SOX2, OCT4, and NANOG expression in cancer cells and M2-like polarization of TAMs." (PMID 39287565, 2024). "Inhibition of Sox2 has demonstrated promising results in targeting lung cancer CSCs." (PMID 38672078, 2024). "In addition, Stage III lung cancer had considerably higher SOX2 antibody expression than those with Stage I lung cancer (P = 0.028)." (PMID 38800369, 2024). "In contrast to these genes, SOX2 plays a role in the repression of ferroptosis, as indicated by the evidence that SOX2 enhanced the resistance of lung cancer cells to ferroptosis by maintaining the level of SLC7A11 and regulating cysteine metabolism and GSH level in lung cancer cells." (PMID 38509680, 2024). "Additionally, ALKBH5 has been reported to facilitate Sox2 expression in lung cancer, MM and endometrial cancer." (PMID 39098905, 2024). "Moreover, LSD1 is required for SOX2 expression in lung cancer H520, A2780, and T47D cells and is positively correlated with SOX2 expression in lung squamous cell carcinoma patient samples." (PMID 38612911, 2024). "CDK1 can also interact with Sox2 to increase the stemness of lung cancer cells." (PMID 38189879, 2024). "Furthermore, tumors expressing high levels of SOX2 were more resistant to ferroptosis, and there was a positive correlation between SLC7A11 expression and SOX2 in both mouse and human lung cancer tissue." (PMID 38994937, 2024). "Indeed, SOX2 expression is stimulated by fibroblast growth factor receptor 1 (FGFR1) activation in lung cancer." (PMID 38612911, 2024). "CDK1 positively regulated the lung cancer cell’s stemness via interacting with Sox2." (PMID 37689745, 2023). "Furthermore, the galectin-3-EGFR complex promotes lung cancer stemness by activating downstream signaling and upregulating Sox-2 expression via c-Myc." (PMID 36823664, 2023). "Furthermore, the SOX2 transcription factor plays a role in both tumor development and the maintenance of pluripotency in human lung cancer." (PMID 38132948, 2023).
lung carcinoma (continued). "Based on the postulated mechanisms, GLI1 inhibition may lead to the downregulation of its target genes, including stemness-related SOX2 and ABCG2 in lung cancer cells, thus underlying its potential therapeutic interference." (PMID 37149646, 2023). "Interestingly, recent studies have confirmed that c-Myc functions as a transcriptional activator of SOX2 by binding to SOX2 gene promoter, and cooperates with SOX2 to maintain stemness and tumorigenicity in breast and lung cancer." (PMID 37147666, 2023). "Overexpression of SOX2 is correlated with FGFR fusion in human lung cancer cells." (PMID 36601474, 2022). "Notwithstanding the multiple systematic meta-analysis that addressed the impact of Sox2, nestin, and vimentin as independent predictors in human lung cancer prognosis, two reports demonstrated the clinicopathological and prognostic significance of the nucleolin expression in lung cancer patients." (PMID 35565346, 2022). "Moreover, SLC7A11 is also upregulated in lung cancer stem cell-like cells and activated by the cell transcription factor SOX2." (PMID 36105219, 2022). "SOX2 was reported to be an oncogene that promoted the malignant behaviours of lung cancer cells." (PMID 35415876, 2022). "SOX2 is related to drug resistance in many types of cancer, including lung cancer." (PMID 35059870, 2022). "In lung cancer, many studies have shown that intracellular transcription factors, such as SOX2, OCT4, and NANOG, are maladjusted and may therefore activate stemness genes and suppress differentiation genes." (PMID 35719973, 2022). "A mouse xenograft model of A549 was used to show that the combination therapy of HM-3 and VNP20009 Sox2 shRNA, could inhibit angiogenesis and slow lung cancer growth." (PMID 33738260, 2021). "SOX2 protein abundance derived from amplification of its locus is common in squamous carcinogenesis and is used clinically to confirm a squamous profile in evaluation of lung cancers." (PMID 34436017, 2021). "In addition, our studies define a new pathway that involves α-KG as a key metabolic signaling intermediate between BCAT1 and the post-transcriptional regulation of SOX2 expression in metastatic lung cancer cells." (PMID 34646394, 2021). "Taken together, our data indicates that BCAT1 plays an important role in driving lung cancer cell metastasis through modulating the expression of stemness factor SOX2 at the post-transcriptional level, and identify α-KG as a key signaling intermediate in this process." (PMID 34646394, 2021). "SOX2 (sex determining region Y)-box 2 is a transcription factor that is essential for maintaining the pluripotency of undifferentiated embryonic stem cells and lung cancer stem cells." (PMID 33738260, 2021). "Furthermore, we demonstrated that knocking down BCAT1 reduces SOX2 expression in another metastatic lung cancer cell line H661." (PMID 34646394, 2021). "It has been shown that the silencing of SOX2 caused apoptosis in some lung cancer cells, but not in noncancerous cells, such as BEAS-2B and NL-20." (PMID 34436030, 2021). "Additionally, some ASCL1 targets were ranked among the top twenty regulators including SOX2 whose overexpression has been clearly described in lung cancers." (PMID 33778495, 2021). "Cell invasion and colony formation assays using A549 human lung cancer cells showed that shRNA against Sox2 could reduce migration, and trigger apoptosis by increasing Bax expression, cleaving caspase 3, and decreasing Bcl2." (PMID 33738260, 2021). "ALDH1A1, Nanog, Oct4, and Sox2 are reported stem cell markers in lung cancer." (PMID 34832894, 2021). "In this study, we found that Apatinib could inhibit the expressions of stemness biomarkers ABCG2, CD24, ICAM-1, OCT4, and SOX2 in lung cancer." (PMID 32849930, 2020). "Notably, the mRNA expression levels of both NANOG and SOX2 were found to be downregulated in subpopulations of cancer stem cells isolated from lung cancer tissue specimens." (PMID 32635524, 2020).
lung carcinoma (continued). "Hedgehog signaling and SOX2 are potential therapeutic targets for CSCs in lung cancer." (PMID 32033067, 2020). "Therefore, we first analyzed the correlation of expression between USPs and stemness transcript factors exemplified by Oct4/Sox2, utilizing clinical lung cancer samples from Oncomine database." (PMID 32549341, 2020). "The IC50 of SOX2‐overexpressing cells was higher than that in normal lung cancer cells." (PMID 32130794, 2020). "In addition to directly binding to target genes, SOX2 regulates gene expression via histone modifications during stem cell differentiation and lung cancer cell plasticity." (PMID 32427884, 2020). "It has been reported that c-Myc could activate SOX2 gene transcription by binding to the SOX2 promoter in lung cancer cells." (PMID 33153498, 2020). "SOX2, a common gene amplified in lung cancer, was expressed in the epithelial cells and enriched in the NCLhigh cells, suggesting a possible role of the undefined NCLhigh cell population as the cell origin of some lung cancers." (PMID 32727470, 2020). "They show the relative expression of both OCT4 and SOX2 is higher in lung cancer cells." (PMID 32111825, 2020). "SOX2 expression levels were estimated and quantified in five commonly used lung cancer cell lines." (PMID 32130794, 2020). "Thus, further studies should be conducted to determine if other molecules exist that affect SOX2 expression in cisplatin‐resistant lung cancer cells." (PMID 32130794, 2020). "SOX2 is believed to be a potential molecular marker for lung cancer." (PMID 30867047, 2019). "In light of the complex actions of SOX2 in regulating normal and tumor cell development, the elucidation of SOX2-dependent pathways may identify new therapeutic vulnerabilities in lung cancer." (PMID 30941314, 2019). "FGFR1 was also highly expressed in NSCLC and promoted tumor formation in lung cancer by interacting with SOX2, Hippo/YAP1 or Hedgehog pathway as our previously work reported 12, 13, 20, while deficiency of KLB did not influence the FGFR1 levels in cultured endothelial cells." (PMID 31695781, 2019). "In addition, higher SOX2 levels have been reported to correlate with poorer prognosis in cancers, such as breast, colorectal, oesophageal, ovarian, prostate, and lung cancer as well as in nasopharyngeal and sinonasal carcinoma." (PMID 30683853, 2019). "SOX2 expression may be correlated with better overall survival in nonsmall cell lung cancer, but worse overall survival in head and neck cancer." (PMID 30693028, 2019). "Nicotine or extracts from each of three brands of e-cigarettes, E-cig 1, E-cig 2, and E-cig 3, could induce Sox2 after 21 h of nicotine stimulation in A549 lung cancer cells." (PMID 30322398, 2018). "Furthermore, Sox2 fosters an epithelial phenotype in lung cancer, which has an etiology comparable to HNSCC with respect to risk factors, through enhanced transcription of the pan-carcinoma marker EpCAM36." (PMID 30275505, 2018). "EGFR-Src-AKT signaling is required to maintain high Sox2 levels in lung cancer stem cells." (PMID 30060526, 2018). "Indeed, SOX2 expression is significantly correlated with that of NFATc2 in this group of human lung cancer." (PMID 28737489, 2017). "The clinical significance of NFATc2/SOX2 coupling was further assessed in human lung cancers." (PMID 28737489, 2017). "Together, the data strongly supported NFATc2/SOX2/ALDH1A1 form a regulatory axis in lung cancer." (PMID 28737489, 2017). "Oct4, Sox2 and Nanog were proposed to be critical markers for lung cancer stem cells." (PMID 28076327, 2017). "Moreover, conditional homozygous overexpression of SOX2 in murine Clara cells induces bronchial epithelial hyperplasia with progression to lung cancer in approximately 50 % of the animals." (PMID 26780934, 2016).
lung carcinoma (continued). "In the present study, we observed that ART, DHA, and ARTS inhibited the expression level of Wnt5-a/b, down-regulated those of LRP6 and Dvl2, and subsequently reduced those of downstream genes mediated by β-catenin (i.e., nanog, sox2, oct3/4, and cyclin D1) in two lung cancer cell lines." (PMID 27119499, 2016). "Finding an effective way to deliver Sox2 shRNA constructs into lung cancer cells may achieve better anti-tumor effect." (PMID 27371094, 2016). "Accordingly, SOX2 affects tumorigenesis and its overexpression increases cell migration and colony formation, while its knockdown impairs cell growth and suppresses metastasis of lung cancer cells." (PMID 26780934, 2016). "By knocking down the expression of Sox2 with shRNA, the growth of lung cancer cells was inhibited." (PMID 27371094, 2016). "Similarly, STAT3 has been reported to be activated upstream of SOX2 in breast and lung cancer stem cells." (PMID 26370982, 2015). "Stemness genes, octamer biding transcription factor 3/4 (OCT4) and/or SRY-box containing gene 2 (SOX2), have been found to bind to the P1 promoter region of CD133 gene loci and ectopic OCT4 or SOX2 expression triggers the CD133P1 activity in the lung cancer cell lines N417, H358, and A549." (PMID 23815814, 2013). "The purpose of this study is to investigate the differential expression and clinical significance of seven stem-cell-associated markers (Bmi1, CD133, CD44, Sox2, Nanog, OCT4 and Msi2) in lung cancer, providing new targets for the diagnosis and treatment of lung cancer." (PMID 23683495, 2013). "Furthermore, hypoxia induced CD133 expression in human lung cancer cells by upregulation of Oct3/4 and Sox2 through HIF-1α and HIF-2α." (PMID 23840432, 2013). "However, Sox2 mRNA knockdown of the human lung cancer stem-like cells/cancer-initiating cells by gene-specific siRNA eliminated tumorigenicity in vitro and in vivo." (PMID 23251245, 2013). "In this study we investigate the prognostic role of SOX2 using automated quantitative immunofluorescence (QIF) in two independent lung cancer cohorts and analyzed the relationship between SOX2 levels and the main clinicopathologic features of patients with lung cancer." (PMID 23620753, 2013). "Recent reports show that Sox2, OCT4 and Nanog are potential diagnostic markers for lung cancer." (PMID 23683495, 2013). "Our study suggests that not only Oct4 but also Sox2 may play an impotent role in this procedure of lung cancer tumorigenesis." (PMID 22837720, 2012). "Furthermore, in the lung cancer tissue, the positive rate for Sox2 and Oct4 was 70.5% and 54.5%, respectively." (PMID 22837720, 2012). "The molecular mechanism of Sox2 gene in promoting development of lung cancer stem cells and enhancing the potential of cancerogenesis might be related to the elevation of the expression of oncogenes c-Myc, Wnt1, Wnt2 and Notch1." (PMID 23443092, 2012). "The correlation of SOX2 with clinical status of patient with lung cancer." (PMID 22615765, 2012). "In view of the important contributions of SOX2 in maintaining the stemness property of CSCs, we hypothesize that SOX2 might govern the transcriptional network of oncogenes to affect the tumorigenesis of lung carcinoma." (PMID 22615765, 2012). "Other than the Sox2 and Sox4, Sox9 and Sox18 also showed oncogenetic properties in lung cancer." (PMID 23443092, 2012). "Possible linkages between them in lung cancer are considered, such as the Sox2-Oct4 complex." (PMID 22837720, 2012).